ENSG00000259522 (novel protein)
Gene: Protein-coding gene on chromosome 14 (24,180,395 to 24,190,416, reverse strand). Ensembl gene ENSG00000259522.
Genetic constraint (gnomAD): Missense variants: 105 observed, 187.11 expected, observed/expected ratio (o/e) 0.56, 90% interval 0.48 to 0.66. Synonymous variants: 67 observed, 72.28 expected, observed/expected ratio (o/e) 0.93, 90% interval 0.76 to 1.14.